TERT (telomerase reverse transcriptase)
Diseases named in the same sentence as TERT in open-access papers (continued):
Sharing a sentence is not in itself a finding about the gene and the disease.
adenocarcinoma (18 papers, 2010 to 2024). A common cancer characterized by the presence of malignant glandular cells. "The strongest risk association was observed between the TERT rs2736100 polymorphism and adenocarcinoma in all genetic models." (PMID 22221621, 2012). "Study of the in vivo effects of expression of RT TERT on tumorigenicity of murine adenocarcinoma 4T1luc2 cells was, therefore, carried on cell lines 4T1luc2_rtTERT_C6 and 4T1luc2_rtTERT_H9." (PMID 32570805, 2020). "Furthermore, we have shown that DNA immunization with TERT fully protects mice against challenge with TERT-expressing adenocarcinoma cells (manuscript in preparation)." (PMID 34067686, 2021). "The re-expression of TERT may indicate progression from bronchiolo-alveolar carcinoma to adenocarcinoma." (PMID 22221621, 2012). "As SNPs at this locus could potentially influence oncogenesis by modulating TERT expression, we examined whether rs7736074 and rs4975596 associate with TERT expression levels in COAD, SKCM, THCA, UCEC, as well as for two subtypes of NSCLC (squamous cell or adenocarcinoma)." (PMID 24152305, 2013). "Adenocarcinoma and SCC of the lung (18% and 40%, respectively) contrast with oral SCC (2%) concerning the presence of TERT amplifications in cohorts with more than 200 patients." (PMID 29751586, 2018). "Several of the identified mGISTIC regions harbored known or putative adenocarcinoma driver candidates, such as EGFR, MDM2, KRAS, MYC, TERT, MET, CCND1, NKX2-1/TITF1, CDK4, ERBB2, ID1, RB1, CDKN2A and PTEN." (PMID 24205279, 2013).
benign tumors (11 papers, 2013 to 2025). "The TERT promoter mutations that usually lead to an increased TERT expression are seldom present in benign tumors." (PMID 28410231, 2017). "However, many studies have demonstrated that TERT promoter mutations and detectable telomerase activity are present in premalignant lesions or even benign tumors." (PMID 36713366, 2022). "These mutations are observed in benign neoplasms and in around 30% of PTC, which are closely linked with TERT and RAS mutations and indicate individuals in advanced TC with a reduced rate of disease-specific survival." (PMID 39558949, 2024). "On the other hand, the presence of TERT expression in benign tumours can be due to the presence of lymphocytic infiltrate and lead to dubious interpretations." (PMID 32659948, 2020). "The presence of lymphocytic infiltration not only affects the evaluation of TERT mRNA expression in benign tumours." (PMID 32659948, 2020). "TERT mRNA expression was detected in 14 of the 83 benign tumours analysed (17% of the FTAs), whereas 47 of the 98 malignant samples were TERT mRNA positive (48%)." (PMID 32659948, 2020). "Among 41 nodules (57.8%) identified with neither RAS, BRAF V600E, nor TERT promoter variants, 17 were benign tumors, 1 was NIFTP, 14 were CPTCs, and 9 were IEFVPTCs." (PMID 38758552, 2024). "Thus, TERT RNA expression has been observed in all the metastasizing PHEOs studied, but it can also be detected in benign tumors; hTERT expression was characterized by 100% sensitivity and better specificity than that of TERT mRNA, and was correlated with high telomerase activity." (PMID 34833055, 2021).
hematological malignancies (11 papers, 2014 to 2021). "Telomerase reverse transcriptase (TERT) promoter mutations have been discovered in solid and hematological malignancies, where they reflect TERT activation and cell-cycle progression." (PMID 29222734, 2018). "There are some TERT promoter polymorphisms associated with increased risk of developing hematological diseases, and even suggested as prognostic markers of survival." (PMID 27618103, 2016). "All-trans retinoic acid (ATRA), a targeted drug used to treat hematological malignancies, can inhibit cell proliferation in telomerase reverse transcriptase (TERT)-hypomethylated OC tissue types, and ATRA may be a new and effective individualized therapy." (PMID 34404407, 2021). "However, hematological malignancies are not reported to be subjects for somatic promoter mutations in the TERT gene." (PMID 27618103, 2016). "Thus, it may be worthwhile to evaluate the therapeutic efficacy of DNMTIs on hematological malignancies based on their induction of TERT inhibition/telomere dysfunction in future clinical trials." (PMID 25682873, 2015).
lip (11 papers, 2011 to 2023). "We identified a strong enrichment of TERT promoter mutations in oral cavity tumors." (PMID 37561583, 2023). "TERT is a well-known factor involved in the progression of colorectal carcinogenesis and higher activity." (PMID 34712603, 2021). "The human 5p15.33 locus contains two well-known genes, the telomerase reverse transcriptase (TERT) and cleft lip and palate transmembrane 1-like (CLPTM1L) genes, which have been implicated in carcinogenesis." (PMID 24386361, 2013). "The region on chromosome 5p15.33 contains two genes, CLPTM1L - cleft lip and palate transmembrane 1 like gene and TERT - human telomerase reverse transcriptase gene." (PMID 21966413, 2011).
neurodegenerative disease (6 papers, 2018 to 2023). A disorder of the central nervous system characterized by gradual and progressive loss of neural tissue and neurologic function. "The result suggests that short telomeres can contribute to brain ageing and neurodegenerative symptoms and that increasing the telomerase/TERT levels in mouse brain had a significant effect on the decrease of cognitive impairment which is an important hallmark of neurodegenerative diseases." (PMID 33946850, 2021). "Oxidative stress is a significant contributor to the development of neurodegenerative diseases and TERT has been found to play a role in addressing these conditions." (PMID 37063844, 2023). "Given the anti-aging and antioxidant effects of TERT, it is essential to further examine the relationship between TERT and various neurodegenerative diseases." (PMID 37063844, 2023). "Upon reviewing the literature, it is evident that there is a scarcity of studies that focus on the role of TERT in neurodegenerative diseases, especially in the context of immune aging." (PMID 37063844, 2023). "This review summarizes the relevant roles of TERT and the potential relationship between T cell senescence and neurodegenerative diseases, in order to provide insights into the pathogenesis of these diseases and pave the way for the development of new therapeutic agents." (PMID 37063844, 2023). "However, there is limited research on the relationship between T cell senescence and neurodegenerative diseases, which has led to a growing interest in exploring the potential link between TERT and T cells in this context." (PMID 37063844, 2023). "Thus, clinical trials with early stages of PD patients or other neurodegenerative diseases such as AD are required to confirm the beneficial effects of increasing telomerase/TERT levels in brains of patients suffering from neurodegenerative diseases." (PMID 33946850, 2021). "Thus, exploring the potential connection between TERT’s antioxidant effects and T cell senescence could be a promising avenue for future research and could offer new insights into the treatment of neurodegenerative diseases." (PMID 37063844, 2023). "However, based on our findings we hypothesise that the telomerase protein TERT might improve protein quality control and thereby protect neurons from toxic proteins such as α-syn in neurodegenerative diseases." (PMID 33188884, 2021). "Meta-analyses showed that the TERT SNP rs2736100 C allele is positively associated with multiple cancerous diseases, while the A allele is positively associated with predisposition to non-cancerous (degenerative) diseases." (PMID 29536006, 2018). "Thus, in addition to extending the shortest telomeres via its canonical telomerase function, the increase of TERT in the brain could be a valuable anti-ageing intervention as well as a novel therapeutic strategy for modifying and ameliorating neurodegenerative diseases such as PD or AD." (PMID 33188884, 2021). "This review summarises the current knowledge about the non-canonical role of the telomerase protein TERT in brain and shows its potential benefit for the amelioration of brain ageing and neurodegenerative diseases such as AD and PD." (PMID 33946850, 2021).
cardiovascular disease (5 papers, 2013 to 2021). "Understanding this enzymes’ functions in these tissues could, in the long run, help to reveal the therapeutic potential of activating TERT in cardiovascular diseases." (PMID 27322328, 2016). "Moreover, recent findings concerning TERT in different mouse models with respect to cardiovascular diseases will be described." (PMID 27322328, 2016). "We discuss the role of defective mitochondrial protein import in the two most common neurodegenerative diseases (Parkinson’s and Alzheimer’s diseases) and cardiovascular diseases (CVD), focusing on cardiolipin and the unique protective role of mitochondrial telomerase reverse transcriptase (TERT)." (PMID 34944035, 2021). "In addition, since the association between the TERT polymorphisms and telomere length could not be evaluated in the ARIC study, a link between increased risk of cardiovascular disease and the possible functional impact of the gene could not be explored further." (PMID 26201603, 2015).
head and neck tumors (3 papers, 2020 to 2025). "TERT promotor mutations were commonly associated with OSCC as compared to other head and neck tumors." (PMID 40307280, 2025). "Summary of studies evaluating the association between head and neck tumors with TERT promoter mutations." (PMID 32850388, 2020). "Our study suggests that in head and neck tumors, TERT promoter mutations could be performed in a screening setting to help clinicians decide for a more aggressive initial treatment accompanied by a closer follow-up, in order to give these patients a better chance to survive." (PMID 32850388, 2020).
hematologic cancer (3 papers, 2022 to 2025). "High expression of TERT is not closely associated with TERT promoter mutations, since such mutations are more frequently observed in solid tumors, whereas reports of these mutations in hematologic cancers are rare." (PMID 39871386, 2025).
metabolic disease (3 papers, 2022 to 2025). A congenital disorder (due to inherited enzyme abnormality) or acquired (due to failure of a metabolically important organ) disorder resulting from an abnormal metabolic process. "Both the TERT mutation (rs7705526) and the TET2 (rs2454206) are reported to significantly correlate with levels of blood pressure in the Common Metabolic Diseases Knowledge Portal (hugeamp.org)." (PMID 36009574, 2022). "We have also reported that inactivation of TERT in APC expedites their telomere attrition, the onset of replicative senescence, and metabolic disease in mice." (PMID 39932851, 2025). "Mice lacking TERT in perivascular progenitor cells have premature metabolic disease, more so if given a high-caloric diet." (PMID 36552277, 2022).
genetic disease (2 papers, 2008 to 2025). "The cell lines reported here, with the removal of the TERT vector, could be used for the production of null mutant rhesus macaque models of human genetic disease using SCNT technology." (PMID 18366794, 2008).
psychiatric diseases (2 papers, 2024 to 2025). "A search in four English databases was conducted from inception to November 2024 to evaluate the association between psychiatric disorders and telomerase activity (TA) or TERT gene expression in peripheral blood." (PMID 40887790, 2025). "Replenishment of TERT could be a common treatment strategy for GCs dysfunction‐associated psychiatric diseases." (PMID 38421107, 2024). "These two studies provide new insights into the understanding of TL in psychiatric disorders that go beyond the sole investigation of TA or TERT gene expression." (PMID 40887790, 2025). "Although telomerase and its catalytic subunit TERT have been suggested to play a central role in TL shortening in psychiatric disorders, more comprehensive investigations of other biological pathways involved in telomere homeostasis are essential to understand the mechanisms at stake." (PMID 40887790, 2025). "Telomere shortening is a phenomenon shared by most psychiatric disorders, leading to the hypothesis of alterations of telomerase activity (TA) and/or TERT expression." (PMID 40887790, 2025). "Supporting the hypothesis that other proteins than TERT may play a role in TL shortening in psychiatric disorders, previous studies have identified two of these proteins as potentially implicated." (PMID 40887790, 2025). "Telomere shortening is shared by all psychiatric disorders and is hypothesized as resulting from decreased telomerase activity (TA) or expression of the TERT (Telomerase Reverse Transcriptase) gene." (PMID 40887790, 2025). "We showed that peripheral blood TA and TERT gene expression do not differ between individuals with psychiatric disorders compared to healthy controls." (PMID 40887790, 2025).
inflammation (1 paper, 2020). Aberrant reaction of the microcirculation characterized by movement of fluid and leukocytes from the blood into extravascular tissues. "For example, reconstitution of TERT in TERT-deficient mice reduced bleomycin-induced and senescence mediated pulmonary inflammation and fibrosis." (PMID 32384619, 2020).
inflammatory myopathies (1 paper, 2023). "Although human endurance athletes lacked detectable levels of telomerase activity and TERT mRNA expression in skeletal muscle, others have demonstrated telomerase activity and TERT protein levels are present, albeit at low levels, in healthy individuals and patients with inflammatory myopathies." (PMID 37041671, 2023). "Interestingly, patients with the shortest telomeres with inflammatory myopathies tended to have the highest telomerase activity and TERT expression indicating a link with inflammation." (PMID 37041671, 2023).
TERT also shares sentences with these, for which no sentence is quoted: papillary carcinoma (15 papers); nevus (8); multiple myeloma (5); chronic lymphocytic leukemia (4); Barrett esophagus (3); breast adenocarcinoma (3); diffuse large B-cell lymphoma (3); hepatitis C (3); inflammatory bowel disease (3); laryngeal tumors (3); mental retardation (3); mental retardation X-linked syndrome (3); mucosal (3); pancreatic neuroendocrine tumor (3); preeclampsia (3); testicular cancer (3); acquired aplastic anemia (2); acute kidney injury (2); acute myocardial infarction (2); Allergy (2); Alpha thalassemia/mental retardation syndrome X-linked (2); anaplastic oligodendroglioma (2); angiosarcoma (2); autoimmune disease (2); benign meningioma (2); breast invasive carcinoma (2); clear cell sarcoma (2); Crohn disease (2); cystic fibrosis (2); dementia (2).
A further 198 diseases each share a sentence with TERT in 2 papers or fewer.